EGFR (epidermal growth factor receptor)
Diseases named in the same sentence as EGFR in open-access papers (continued):
Sharing a sentence is not in itself a finding about the gene and the disease.
tumor (continued). "Therefore, we developed an approach for a reliable high-resolution quantitative genetic analysis of isolated single tumor cells on the example of the EGFR gene." (PMID 22140428, 2011). "The same clinical material displayed overexpression of EGFR in tumor tissue." (PMID 22194989, 2011). "Furthermore, there were clear differences in expression levels for Aurora-A and EGFR within the patient tumor tissue assessed." (PMID 21865609, 2011). "Our data, which are mostly concordant with previous observations, suggest that EGFR overexpression may result in a more aggressive tumour behaviour, through deregulated function of these genes." (PMID 21266046, 2011). "EGFR blockade has hence been proposed to inhibit tumor growth." (PMID 21917153, 2011). "This suggests that it may be of limited value to know the EGFR status in a biopsy from just one tumour lesion." (PMID 22095231, 2011). "Conversely, agents that can help to mitigate apoptotic potential could decrease the sensitivity of tumor cells to the EGFR inhibitors, which should be avoided to use clinically." (PMID 22194952, 2011). "TKIs effectively prevent auto-phosphorylation of EGFR and Her2 in tumor cells, however, the transphosphorylation of Her3 is only transiently suppressed and Her3 ultimately escapes inhibition by TKIs in Her2 over-expressing tumor cells." (PMID 21801427, 2011). "A total of 86 (63.7%) patients with wild/wild tumours and five (33.3%) patients with BRAF mutation-positive tumours received anti-EGFR therapy, whereas few patients with KRAS12 or KRAS13 mutations received anti-EGFR therapy (1.9% and 3.8%, respectively)." (PMID 21285991, 2011). "Interestingly, all four monotherapy responders had tumours in which EGFR was overexpressed, two of which also showed HER2 expression and one that showed HER2 gene amplification." (PMID 21829197, 2011). "This phenomenon can lead to improvement of the efficacy of radiotherapy, likely because inhibition of EGFR signaling in tumor cells decreases cell proliferation, accelerates apoptosis, interferes with the cell cycle, and extends the time required for DNA repair after radiation." (PMID 21689422, 2011). "Unfortunately, tumour tissue was not assessed for EGFR mutation analysis due to the absence of informed consent for mutational analyses as the trial was conducted before significance of EGFR mutations were reported." (PMID 21878940, 2011). "In tumour areas, EGFR overexpression was found in 36 patient specimens (36%)." (PMID 21266046, 2011). "Tumours were classified into four categories with respect to their mean EGFR gene copy numbers." (PMID 22152101, 2011). "The xenografts also showed a significant reduction in blood vessel counts following several rounds of cetuximab treatment, indicating that the tumor-promoting effects of EGFR overexpression may be mediated through VEGF stimulation and tumor angiogenesis." (PMID 21399234, 2011). "Our findings in this study indicate that apoptosis inducers and EGFR-targeted inhibitors enhance mitochondrial translocalization of both EGFR and EGFRvIII and that mitochondrial accumulation of these receptors contributes to tumor drug resistance." (PMID 21388543, 2011). "This cooperative role of EGFR with other receptors in tumor growth could be exploited for therapeutic interventions." (PMID 24212818, 2011). "PCR-based methods are considered highly sensitive and also to demonstrate strong specificity via the design of primers that detect mRNA expression of tumor-specific genes such as cytokeratin (CK)-20, uroplakin (UP) II, and epidermal growth factor receptor (EGFR)." (PMID 21816094, 2011). "Furthermore, we have demonstrated that CAF secretion of NRG-1 actively circumvents the inhibitory effect of erlotinib and promotes tumour growth providing an ‘escape’ mechanism to EGFR-targeted therapy." (PMID 21792199, 2011).
tumor (continued). "Several lines of evidence indicate that the EGFr signaling pathway may be an important factor in determining tumor cell response to ionizing radiation." (PMID 22077956, 2011). "Radiation therapy may enhance the EGFr intracellular activation pathways, which in turn may induce proliferation, blockage of apoptosis and contribute to promote the tumor growth." (PMID 22077956, 2011). "EGFR positivity was 25.5% in the primary tumor and 41.7% in the metastases." (PMID 21773035, 2011). "No mutations were detected in either the EGFR gene or the KRAS gene in the primary tumor from this patient." (PMID 21414214, 2011). "Consequently, adaptive immune responses to the tumor peptides are inefficient, and frequencies of EGFR-specific CTL remain low." (PMID 21970318, 2011). "Efficiently blocking the interaction between EGF and EGFR could inhibit cell proliferation and tumor growth." (PMID 21687663, 2011). "The EGFR is involved in signaling pathways controlling cell growth, differentiation, and proliferation and is expressed in many different types of normal tissues as well as several tumor types, including CRC." (PMID 21437184, 2011). "Selective inhibition of Src and Fyn limited EGFR-dependent tumor cell motility." (PMID 21776389, 2011). "We found significantly more intense membrane staining for EGFR in tumours of high grade and stage." (PMID 21364580, 2011). "Another important issue is whether treatment with EGFR TKIs should be denied to patients with tumours showing wild-type EGFR gene." (PMID 21654681, 2011). "Twenty-five of the 35 SCCs showed positive expression of p-EGFR in tumor cells." (PMID 21197106, 2011). "Interestingly, only the combination of advanced tumor size (T2-4) and high EGFR score (> 7) was followed by a significant increase of EGFR-specific CTL." (PMID 21970318, 2011). "All tumor samples were positive for EGFR, and 5 samples showed an EGFR score of 9 or higher." (PMID 21970318, 2011). "The EGFR pathway signals through Kras/Braf and although EGFR/c-Erb-B2 amplifications are rare in CRC, gain-of-function mutations in KRAS/BRAF are extremely common and are seen in up to 60% of tumours." (PMID 21698197, 2011). "As demonstrated by the LNCap and RWPE studies, genistein-activated ERβ may stimulate the EGFR/Src signaling pathway, which leads to increased proliferation, reduced apoptosis and tumor progression in our model." (PMID 21603581, 2011). "There are several reports on EGFR as an adverse prognostic indicator in different tumor types." (PMID 21756326, 2011). "In addition, the existence of EGFR independent signaling for Stat3 activation has been reported, enhancing the importance of Stat3 activation in tumor growth." (PMID 21197106, 2011). "Conversely, EGFR expression was enhanced in the tumor material." (PMID 22194989, 2011). "A set of interactions between these two pathways, as well as positive and negative feedback loops, compose a complicated network which mediates the impact of EGFR and other transmembrane receptors on cell proliferation, inhibition of apoptosis, tumor growth, and invasiveness." (PMID 21785682, 2011). "Moreover, the number of pathologically positive lymph nodes and EGFR numerical aberrations of the primary tumour were also shown to be excellent predictors of ECS in OSCCs." (PMID 21304522, 2011). "In vitro studies demonstrated that treatment with Cetuximab inhibited ligand-induced EGFR autophosphorylation and EGFR-dependent cellular response, including extracellular acidification, cell proliferation, and production of angiogenic factors by tumour cells." (PMID 21595970, 2011). "This conundrum suggests that EGFR might contribute to tumor progression independently of its kinase activity." (PMID 22035226, 2011).
tumor (continued). "The biology underlying tumor resistance to EGFR-targeted therapy is thus complex and remains not well understood." (PMID 21388543, 2011). "Recent advances in the mechanisms of oncogenesis have revealed that the constitutive activation of the EGFR/ERK pathway allows the tumor cells to bypass regulatory check points that normally balance cell growth and cell apoptosis thereby activating cell cycle entry." (PMID 22096483, 2011). "Furthermore, binding of Nimotuzumab Fab fragments was detected only for A431 cells, having the highest EGFR expression level, whereas Cetuximab Fab fragments bound also to tumor cells with lower EGFR expression levels." (PMID 24212794, 2011). "In addition, treatment with the EGFR-targeted lonidamine/paclitaxel nanoparticles decreased tumor density and altered the MDR phenotype of the tumor xenografts." (PMID 21931642, 2011). "Altogether, route of DNA immunization and its formulation could represent an important element in the design of EGFR DNA vaccine against EGFR-positive tumor." (PMID 21211062, 2011). "In this regard, EGFR blockers appear to inhibit tumor cell death via multiple mechanisms." (PMID 22242139, 2011). "Furthermore, miR-146a, -193b and -29c have been shown to inhibit tumor cell invasiveness and metastatic potential by repressing EGFR, urokinase-type plasminogen activator and extracellular matrix proteins, respectively." (PMID 21829663, 2011). "In addition to molecular alterations of the EGFR gene, activation of EGFR downstream effectors can lead to tumor formation/progression." (PMID 21403829, 2011). "HER3 signaling through heterodimerization is an important growth-promoting mechanism in several tumor types and may be a principal resistance mechanism by which EGFR and HER2 expressing tumors elude targeted therapies." (PMID 21297994, 2011). "FISH-positive status may be a surrogate marker of generalised genetic instability in the tumour or of additional genes that are co-amplified with EGFR." (PMID 21304522, 2011). "These considerations suggested PTEN might also be a determinant of the efficacy of EGFR TKIs in EGFR wild-type tumours and prompted us to evaluate PTEN and PIK3CA gene copy number in our gefitinib-treated patients." (PMID 22095222, 2011). "Forty-five patients had sufficient tumor samples for evaluation of EGFR GCN by FISH." (PMID 21352589, 2011). "High glucose levels have recently been shown to transactivate EGFR in benign diseases." (PMID 22087246, 2011). "Immunohistochemistry showed a strong EGFR staining in ~90% of tumor cells." (PMID 21970335, 2011). "This is the first long-term study of these treatment approaches in an autochthonous model of K-ras wild type intestinal tumourigenesis to examine tumour phenotypic change, adding significantly to the body of evidence supporting the importance of EGFR and IGF1R interactions." (PMID 21811251, 2011). "Combined approaches targeting EGFR dysfunction may be useful for patients with EGFR methylated tumours and could represent the basis for prospective studies aiming to compare clinical response with EGFR directed therapeutic agents." (PMID 21559018, 2011). "No consistent histopathological effects were observed in skin biopsies and various biomarkers of EGFR-signalling and serum levels of regulators of (tumour-)angiogenesis also remained essentially unchanged, even in patients experiencing obvious on-target side effects such as diarrhoea and skin rash." (PMID 20823884, 2010). "Tumour cells comprised a functional EGFR, no activating mutations in exons 18–21, and resistance to RAD001 monotherapy." (PMID 20683448, 2010). "Similarly, some of the 768 5NP tumours will be misclassified CBP tumours because data on EGFR were missing." (PMID 20520800, 2010). "The HR for PFS also favored vandetanib arm regardless of baseline tumor and blood biomarker subgroups, with few exceptions in cases with negative EGFR gene amplification and positive KRAS mutation." (PMID 20433767, 2010).
tumor (continued). "Interestingly, these effects were observed even on T790M-harbouring tumours that confer resistance to an EGFR inhibitor such as Erlotinib." (PMID 20628392, 2010). "They tested these antibodies in a series of cell lines and in tumor tissues from patients with primary NSCLC, with known and unknown EGFR mutations, comparing the IHC results with DNA sequencing." (PMID 21167064, 2010). "Statistically significant OS survival for GBT was not demonstrated regardless of tumor histology (adenocarcinoma vs. non-adenocarcinoma), or EGFR mutation status." (PMID 20835310, 2010). "EGFR positive cells were often seen localized at the periphery of tumor nests." (PMID 20579333, 2010). "This paradigm exemplified for EGFR targeted therapy, is becoming the prevalent one in anticancer drug development where stratification of patients is performed according to the molecular characterization of their tumor." (PMID 24281115, 2010). "Furthermore, radiation therapy resulted in an increased expression of both VEGFR-2 and EGFR in lung tumours, leading to tumour proliferation and survival." (PMID 20628392, 2010). "Regarding thedata suggesting that rash may be a biomarker for the tumor's response to EGFR inhibition, this dose–toxicity relationship suggests the need for future study of dose escalation for the development of the rash." (PMID 20302205, 2010). "However, we examined the prognosis of the subset of tumours expressing both EGFR and phospho-EGFR compared with EGFR alone." (PMID 19997103, 2010). "Some series on lung MECs have shown lack of EGFR mutations in these tumours and a percentage of chromosome 7 polysomy of 17%, similar to the results in our series." (PMID 20664595, 2010). "Moreover polymorphism of EGFR has been shown to predict tumour response to CTRT and locoregional tumour recurrence after CTRT." (PMID 20842128, 2010). "Other factors such as, EGFR amplification, epiregulin and amphiregulin expression, nuclear factor-kB tumor expression, PTEN, BRAF or PIK3CA were also suggested to predict response to cetuximab but these additional biomarkers require further validation before incorporation into clinical practice." (PMID 20591136, 2010). "Encouragingly, we found that the resultant fusion protein TGFαL3SEAD227A could bind to EGFR-expressing tumour cells and exhibited an apparent growth inhibitory effect on the tumour cells, both in vitro and in vivo." (PMID 21176167, 2010). "Further, we have investigated whether FAAH-IR is correlated with other pathogenetic and prognostic variables, such as the local tumour stage number and the immunoreactive score for phosphorylated epidermal growth factor receptor (pEGFR)." (PMID 20808855, 2010). "In addition, EGFR signaling regulates the synthesis and secretion of several different angiogenic growth factors in tumor cells, including vascular endothelial growth factor (VEGF), interleukin-8 (IL-8), and basic fibroblast growth factor (bFGF)." (PMID 21087480, 2010). "Certainly, there are targeted treatments that have been shown to have activity in other EGFR-expressing cancers that need assessment in this tumour type, and biomarkers that have been shown to be helpful in other cancer sites should be prioritised for assessment." (PMID 21063399, 2010). "EGFR intensity was unrelated to patient age, gender, or tumour site." (PMID 19997103, 2010). "Additionally, to specifically target tumor cells, the pegylated gold nanoparticles were then conjugated with an antibody against epidermal growth factor receptor, which is sometimes overexpressed in certain types of cancer cells." (PMID 21180459, 2010). "Interestingly in this erlotinib trial, the high EGFR expressing tumor group experienced a 2-fold longer survival, but study did not interrogate tumors for EGFR mutations." (PMID 20942962, 2010). "An increased EGFR-GCN was present in 60/101 (59%) patient tumor samples." (PMID 20398370, 2010). "In tumour 4, for example, 8 expressed genes were co-amplified with the EGFR gene." (PMID 21170331, 2010).
tumor (continued). "Translation of these studies to the clinic confirmed lack of activity of anti-EGFR antibodies like cetuximab or panitumumab in colon cancer tumours with K-RAS mutations." (PMID 20670437, 2010). "Several in vitro and in vivo studies have shown that this chimeric IgG1 mAb binds to the antigen, the EGFR, on the surface of tumor cells while its Fc portion binds to the immune effector cells through FCγ R. Consequently, this binding activates the immune cells leading to tumor cells killing." (PMID 20591136, 2010). "Both are c-Src mediated downstream targets of EGFR and crucial for tumour progression." (PMID 21152443, 2010). "This methodological approach could be of clinical interest in the diagnosis of lung nodules since it may reduce the undetermined diagnoses distinguishing tumor histotype known to better respond to anti-EGFR targeted therapies." (PMID 20843314, 2010). "Tumor budding may also be a predictive factor in metastatic colorectal cancer patients treated with anti-EGFR therapies." (PMID 21317460, 2010). "Thus, EGFR signaling has become an important target in anticancer drug development due to its ability to suppress apoptosis and to control tumor cell proliferation and migration." (PMID 20509930, 2010). "In a phase II study of 148 patients with EGFR-positive mCRC, grades 2–4 skin toxicity was associated with longer PFS (HR 0.67; 95% CI 0.50 to 0.90) and OS (HR 0.72; 95% CI 0.54 to 0.97) compared with grades 0–1 skin toxicity." (PMID 20680104, 2010). "This new knowledge could facilitate the development of rational combinatorial therapies to sensitize tumor cells toward EGFR-targeted therapies." (PMID 20037743, 2010). "However, there was a reduction in phosphorylated EGFR and phospho-extracellular signal-regulated kinase in tumor tissue after treatment." (PMID 20184776, 2010). "However, FISH analysis to determine EGFR gene copy number changes revealed that only complete circumferential immunostaining of the tumour cell membranes using the EGFR113 antibody was a very specific and sensitive marker for amplification of the EGFR gene." (PMID 20502457, 2010). "The activation of epidermal growth factor receptor (EGFR) and the various downstream targets, such as Ras, Raf, MEK and ERK, are deeply implicated in the pathogenesis of PaCa with malignant transformation and enhanced tumour aggressiveness." (PMID 20551957, 2010). "Moreover, we proposed that an exploratory tissue-based study would provide evidence for the relation of HPV infection and EGFR signaling in this tumor type and serve as a guide for clinical trials investigating targeted agents or other therapeutic strategies." (PMID 20498858, 2010). "The molecular mechanism underlying MKP-1-mediated resistance to anti-cancer drugs is in part due to the activation of JNK-driven apoptosis by several anti-tumour agents such as anthracyclines, taxanes, cisplatin, proteasome inhibitors and more recently anti-EGFR drugs." (PMID 20234366, 2010). "The anti-tumor activity of panitumumab was established in a multicentre, phase II study of mCRC patients with EGFR tumor expression levels of 10% or higher who had progressed during or following treatment with fluoropyrimidine, irinotecan, and oxaliplatin treatment." (PMID 20680105, 2010). "Notably, in some serial sections of tumor cells, there was high EGFR immunoreactivity that was accompanied by cytoplasmic and nuclear β-catenin staining and high cyclin D1 immunostaining." (PMID 20302655, 2010). "In addition, EGFR differentially modulates the PI3K/AKT pathway in regulating tumor cell growth and dormancy." (PMID 20428086, 2010). "Quantification of the intensity of the bands showed that the EGFR protein was always more abundant in tumours where the gene was amplified than in control tumours, but the relationship between EGFR mRNA and protein accumulation was loose in some tumours." (PMID 21170331, 2010).